CCL20 (C-C motif chemokine ligand 20)
Diseases named in the same sentence as CCL20 in open-access papers (continued):
Sharing a sentence is not in itself a finding about the gene and the disease.
colorectal cancer (continued). "For example, colorectal cancer cells highly secrete CCL20 to attract regulatory T cells (Tregs) into the tumor microenvironment, which will enhance the chemoresistance of cancer." (PMID 35864953, 2022). "In colorectal cancer, CCL20 in collaboration with C-X-C motif chemokine ligand (CXCL8), promoted tumor metastasis through EMT." (PMID 34569432, 2021). "In vivo, 5-FU treatment elevated the expression of CCL20 in colorectal cancer cells (CRC) by activating FOXO1/CEBPB/NF-κB signaling, which promoted the recruitment of Tregs within TME." (PMID 34095111, 2021). "CCL20 secreted by colorectal cancer cells activating FOXO1/CEBPB/NF-κB signaling, promoting the recruitment of Tregs." (PMID 34095111, 2021). "In mice bearing colorectal cancer, TAMs secrete C-C motif chemokine ligand 20 (CCL20) to recruit Tregs that promote the development of cancer." (PMID 34359674, 2021). "In concordance, the CCL20 secreted by colorectal cancer (CRC) cells can also recruit regulatory T cells (Tregs) to promote chemoresistance via a FOXO1/CEBPB/NF-κB/CCL20 signaling loop in these cells." (PMID 33483477, 2021). "Serum CCL20 was identified as independent prognostic markers for colorectal cancer, which also exhibited a good performance in the diagnosis of early stage disease." (PMID 33123272, 2020). "In particular, F. nucleatum induced CCL20 protein expression in in vitro colorectal cancer cells and stimulated macrophage activation and migration." (PMID 32148479, 2020). "In this study, we found that colorectal cancer cell-derived chemokine (C-C motif) ligand 20 (CCL20) induced recruitment of Tregs via FOXO1/CEBPB/NF-κB signaling, and that Tregs further promoted chemoresistance of CRC." (PMID 31395078, 2019). "Based on a known synergistic relationship between CXCL8 and CCL20 that promotes poor survival outcome in colorectal cancer, these two genes were further investigated as possible prognostic factors in GBM." (PMID 29983870, 2018). "CXCL8 is an angiogenic factor in many cancers, CCL20 promotes malignancy, and together they synergize to promote a poor survival outcome via induction of epithelial-mesenchymal transition in colorectal cancer." (PMID 29983870, 2018). "Cooperative induction of EMT in colorectal cancer cells has been shown upon IL‐8 and CCL20 treatment, in conditions in which each individual treatment failed to induce EMT." (PMID 28599100, 2017). "Supportively, the authors also show that colorectal cancer cells undergo EMT changes when exposed to CCL20 in vitro." (PMID 28599100, 2017). "The oncogenic role of CCL20 has been characterized to be the promotion of tumor cell invasion through the up-regulation of MMP-9 in colorectal cancer cells and pancreatic adenocarcinoma." (PMID 26300991, 2015). "Levels of CCL20 were measured in matched samples of colorectal cancer and adjacent uninvolved colon by ELISA." (PMID 24866282, 2014). "The proliferative activity of CCL20 on the colorectal cancer cell lines was further confirmed using the 3H-thymidine incorporation assay." (PMID 24866282, 2014). "A possible role of CCL20 in the liver mediating metastasis of CCR6-expressing colorectal cancer cells has been explored." (PMID 24866282, 2014). "Stimulation of MC38 colorectal cancer cells with CCL20 resulted in a surge of CCL20 production at 30 minutes with a 2-fold increase by 60 minutes." (PMID 24866282, 2014). "Recently, involvement of the chemokine/receptor system CCL20/CCR6 in colorectal cancer (CRC) progression was shown." (PMID 24559209, 2014). "We further confirmed that CCL20 induces proliferation in the murine and human colorectal cancer cell lines as has been shown by other groups for human colorectal cancer cell lines." (PMID 24866282, 2014). "The chemokine receptor CCR6 is expressed in colorectal cancer and stimulation by the chemokine ligand CCL20 promotes proliferation of colorectal cancer cells." (PMID 24259307, 2013).
colorectal cancer (continued). "The miR-21 functionally interacts with the 3′UTR of CCL20 mRNA in colorectal cancer cells, resulting in downregulation of CCL20." (PMID 23800251, 2013). "For example, F. nucleatum enriched in colorectal cancer cells (CRC) can upregulate CCL20." (PMID 39985603, 2025). "Colorectal cancer (CRC) cells releasing CCL20 attracted Tregs, fostering chemoresistance through FOXO1/CEBPB/NF-κB signaling, which could be a promising strategy for treating CRC." (PMID 39143228, 2025). "In addition, six homeostatic chemokines, CXCL12, CCL1, CCL20, CCL25, CCL27, and CXCL11, were upregulated in the peripheral blood of patients with advanced colorectal cancer, which has also been reported to be associated with tumor progression." (PMID 37063892, 2023). "CCL20 induced proliferation and migration of colorectal cancer epithelial cells." (PMID 37889013, 2023). "CCL20 plays a crucial role in colorectal cancer and thyroid cancer." (PMID 32732864, 2020). "Moreover, CCL20/CCR6 apparently­ plays a role in organ selective liver metastasis of colorectal cancer." (PMID 30603057, 2018). "Furthermore, a recent study has reported that tumour-associated macrophages (TAMs) can produce CCL20, resulting in increased recruitment of CCR6+ regulatory T cells, and promote colorectal cancer development in mice." (PMID 28798316, 2017). "Having shown an auto-feedback loop in CCL20 production, we sought to confirm that CCL20 could induce proliferation of colorectal cancer cells." (PMID 24866282, 2014). "CCL20 similarly promoted proliferation in the human colorectal cancer cell lines HT29 and Hct116." (PMID 24866282, 2014). "Furthermore, direct effects of CCL20 in increasing proliferation and invasion in colorectal cancer cell lines have been demonstrated in vitro." (PMID 24866282, 2014). "Interactions between the inflammatory chemokine CCL20 and its receptor CCR6 have been associated with colorectal cancer growth and metastasis, however, a causal role for CCL20 signaling through CCR6 in promoting intestinal carcinogenesis has not been demonstrated in vivo." (PMID 24866282, 2014). "There is also one report of CCL20 recruiting Treg cells in an induced colorectal cancer model." (PMID 24156623, 2013). "Also, CCL20 is highly expressed in colorectal cancer cells and contributes to cancer progression." (PMID 32732864, 2020). "Furthermore, CCL20 had a direct mitogenic effect on colorectal cancer cells." (PMID 24866282, 2014). "FBXW7 inhibits colorectal cancer by downregulating ENO1, reducing CCL20, lactate, proliferation, and migration." (PMID 41373479, 2025). "In colorectal cancer, FOXO1/C/EBPβ/NF-κB signaling is required for CCL20-dependent recruitment of regulatory T cells, which confer chemoresistance to 5-fluorouracil." (PMID 36761942, 2023). "Many studies defined CCL20 and its specific receptor CCR6 as prognostic markers and potential interventional targets, including colorectal cancer 5, breast cancer 6, and prostate cancer." (PMID 35864953, 2022). "Treg cells are also recruited by the CCL20/macrophage inflammatory protein 3α (MIP-3α)→CCR6 axis, as shown in research on colorectal cancer, hepatocellular carcinoma, and non-small-cell lung carcinoma models." (PMID 33114763, 2020). "Similar kinetics of CCL20 production were demonstrated by the human colorectal cancer cell lines HT29 and Hct116 when exposed to CCL20." (PMID 24866282, 2014). "The expression of CCL20 and CCR6 has been documented in several tumor types including colorectal cancer." (PMID 24866282, 2014). "In sporadic colorectal cancer, CCL20/CCR6 signaling has been shown to play a role in the proliferation and migration of colorectal cancer cells and in the promotion of liver metastasis via the autocrine and paracrine functions." (PMID 24179507, 2013).
colorectal cancer (continued). "Elevated CCL20 production and its receptor CCR6 have been related to the progression of a variety of human cancers, including liver cancer, colorectal cancer, breast cancer, and kidney cancer, and also indirectly modulates the function of immune cells in response to inflammatory diseases." (PMID 38468450, 2024). "Among them, CCL20 and CXCL8, both of which could promote the migration and metastasis of colorectal cancer cells, were validated to be upregulated by F. nucleatum infection." (PMID 37814323, 2023). "Furthermore, CEBPB also interacts with FOXO1, NF-kappa B, and CCL20, and FOXO1/CEBPB/NF-kappa B/CCL20 axis has been reported as a target for Colorectal cancer treatment." (PMID 34490085, 2021). "CCL20, which is known to contribute to the progression of many cancers, mediates T-reg infiltration into the tumor microenvironment and facilitates cancer progression and poor prognosis in hepatocellular carcinoma (HCC) and colorectal cancer patients." (PMID 34183723, 2021). "Moreover, stimulation with CCL20 led to the activation of the ERK‐MAP kinase and Act pathways in colorectal cancer cells." (PMID 26968871, 2016). "Expression of CCL20 and CCR6 has been observed in several malignancies including colorectal cancer." (PMID 24866282, 2014). "In order to determine whether signaling through CCR6 causes production of CCL20, we used ELISA to assay levels of CCL20 in the supernatant of MC38 murine colorectal cancer cells and splenocytes isolated either from wild-type or CCR6KO mice upon stimulation with CCL20." (PMID 24866282, 2014). "For example, CCL20, by binding to CCR6, regulates the ability of cells to migrate and invade by activating the RhoA pathway in colorectal cancer, a role not commonly seen in other chemokines." (PMID 38791448, 2024).
breast cancer (62 papers, 2009 to 2025). A primary or metastatic malignant neoplasm involving the breast. "In various tumor entities, such as cervical carcinoma, pancreatic ductal adenocarcinoma, cutaneous squamous cell carcinoma and breast cancer, a high expression of CCL20 in the tumor tissue was associated with tumor progression." (PMID 38730689, 2024). "It has been demonstrated that increased expression of CCL20 is associated with increased expression of p-ERK in human breast cancer; melanoma; and head and neck squamous cell carcinoma tumor tissue." (PMID 34853656, 2021). "Despite the novelty of our findings, further in vivo studies will be required to explain the underlying mechanism by which CCL20-TANs-PD-L1 network influences immunosuppression in breast cancer." (PMID 34519637, 2021). "In a recent study, high expression of CCL20 was associated with an increased homing of FOXP3 into breast cancer tissues." (PMID 34569432, 2021). "Recently, however, CCL20 has also been associated with poor breast cancer prognosis." (PMID 32707869, 2020). "Thus, CCL20 may be a key factor for the acceleration of breast cancer metastasis and related bone loss." (PMID 28851919, 2017). "It has been shown that high expression of CCL20 in breast cancer cells can potentiate the differentiation and expansion of granulocyte-monocyte progenitors into polymorphonuclear myeloid-derived suppressor cells (PMN-MDSCs) via CCR6." (PMID 39985603, 2025). "Breast cancer cells promote tumor-derived CCL20 and upregulate PD-L1 expression on neutrophils to exacerbate T cell immunosuppression." (PMID 39071494, 2024). "In conclusion, we discovered that the CCL20 overexpression in breast cancer cells significantly promoted the PMN-MDSC expansion." (PMID 36859354, 2023). "In breast cancer, tumor-derived CCL20 has been recently reported to signal on CCR6 in precursor macrophages, promote PMN-MDSC expansion and exert pro-tumor effects." (PMID 37398643, 2023). "Bioinformatic analysis showed that CXCL2 was positively related to CCL20 in breast cancer patients (p value = 8.4e-31, R = 0.34), and CXCL2 was abundant and highly secreted by PMN-MDSCs in CCL20-overexpressing tumors." (PMID 36859354, 2023). "The CCL20-modulated PMN-MDSCs in TME played indispensable roles in promoting breast cancer cell stemness." (PMID 36859354, 2023). "CCL20 overexpression was confirmed at mRNA level by qRT-PCR and at the protein level in the blood serum of mice bearing CCL20-overexpressing breast cancer cell orthotopic allograft tumors by mouse CCL20 ELISA kit." (PMID 36859354, 2023). "We investigated the key mediator in CCL20-modulated PMN-MDSCs that conveyed breast cancer cell stemness." (PMID 36859354, 2023). "Breast cancer cells can chemoattract CD34+ progenitor cells through CCL20/MIP3α and promote the differentiation of progenitor cells into langerin+ DCs depending upon the level of TGF-β present." (PMID 36160158, 2022). "In an in vitro model of human breast cancer, tumor-derived CCL20 activated and up-regulated PD-L1 expression on TANs, which suppressed T cells in a PD-L1-dependent manner." (PMID 36016960, 2022). "CCL20 contributes to the progression of many cancers, such as liver cancer, colon cancer, breast cancer, pancreatic cancer, and gastric cancer." (PMID 35108275, 2022). "For example, CCL20, increased in serum from animals with MLL tumors, has been shown to be highly expressed in breast cancer models, and inhibition of CCL20 expression or depletion of the CCL20 receptor gene (Ccr6) reduce macrophage infiltration in xenografts." (PMID 35551231, 2022). "CCL20 is also frequently expressed by various types of cancer including hepatocellular carcinoma, breast cancer, colon cancer, pancreatic cancer, prostate cancer, lung cancer, and renal cell carcinoma." (PMID 34885241, 2021).
breast cancer (continued). "This review provides the current knowledge on how CCL20 interacts with breast cancer cells to influence tumor progression via immunosuppression, angiogenesis, epithelial to mesenchymal transition, migration/invasion and chemoresistance." (PMID 34569432, 2021). "Collectively, this review suggests that CCL20 plays essential roles in the oncogenesis processes of breast cancer." (PMID 34569432, 2021). "In this research, we showed for the first time how tumor-derived CCL20 induces immunosuppressive neutrophils to inhibit T cell immunity in breast cancer." (PMID 34519637, 2021). "Herein, neutrophils isolated from peripheral blood of healthy donors were treated with supernatants from breast cancer cell lines or recombinant human CCL20." (PMID 34519637, 2021). "To evaluate the functions of tumor-derived CCL20 on neutrophils, we determined the viability and expression of PD-L1 on neutrophils treated with supernatants from breast cancer cell lines and recombinant human CCL20 (rhCCL20)." (PMID 34519637, 2021). "Neutrophils were stimulated with recombinant human CCL20 and supernatants from breast cancer cell lines for 10 hours." (PMID 34519637, 2021). "The signal pathways regulating the actions of CCL20 in breast cancer are diverse and complex, where the activation of a pathway signals several other downstream pathways." (PMID 34569432, 2021). "The expression of CCL20 has been reported to be increased in tumor tissues of many types of cancer including breast cancer, colon cancer, skin cancer, oral cancer, and prostate cancer." (PMID 34885241, 2021). "In aortic ring assay, a robust method for determining angiogenesis, CCL20 directly induced angiogenic microvessel aortic sprouting in primary breast cancer cells." (PMID 34569432, 2021). "This review summarized the emerging roles of CCL20 and the underlying signaling regulating the tumor-promoting functions of CCL20 in breast cancer." (PMID 34569432, 2021). "In breast cancer, HuR regulated the expression of CCL20 to promote invasion of MDA-MB-231 cells and osteolytic bone metastasis in tumor-bearing mice." (PMID 34569432, 2021). "CCL20 expression is also upregulated in tumour cells isolated from melanoma, breast cancer, colon carcinoma and head and neck squamous cell carcinoma (HNSCC) patients, in conjunction with activation of the EGFR/Ras-signalling pathway." (PMID 32601464, 2020). "We observed significantly higher expression of CCL20 in breast cancer metastases compared with healthy mammary tissue." (PMID 32601464, 2020). "Higher expression of CCL7, CCL11 and CCL20 in AA breast cancer patients has been shown to correlate with higher overall survival and better prognoses." (PMID 32824813, 2020). "CCL20 promotes self-renewal and maintenance of breast cancer stem cells and breast cancer stem-like cells by activating p65 nuclear factor kappa B (NF-κB) via protein kinase C or p38 mitogen-activated protein kinase." (PMID 32707869, 2020). "Among patients with breast cancer, those with high CCL20 expression have significantly lower overall survival and metastasis-free survival." (PMID 32707869, 2020). "In basal-like TN breast cancer, CCL20 promotes bone metastasis by raising the secretion of MMP-2/9 and increasing the receptor activator of nuclear factors-kappa B (NF-κB) ligand/osteoprotegerin ratio in breast cancer and osteoblastic cells." (PMID 33489906, 2020). "Next, we investigated CCL20 mRNA expression in tumour biopsies taken from patients suffering from breast cancer, melanoma and HNSCC." (PMID 32601464, 2020). "In the 156 breast cancer patients, CCL20 expression was significantly correlated with high histological grade (P = .008), positive lymph node metastases (P = .02), positive HER2 (P = .02), and high Ki67 index (P = 0.03)." (PMID 31852159, 2019). "We evaluated the prognostic significance of FOXP3+ TILs and CCL20 expression in breast cancer and conducted clinical follow-ups." (PMID 31852159, 2019).